GAB2 (GRB2 associated binding protein 2)
Diseases named in the same sentence as GAB2 in open-access papers (continued):
Sharing a sentence is not in itself a finding about the gene and the disease.
cancer (continued). "The interaction between the C-SH3 domain of Grb2 and Gab2 is of crucial importance for cell physiology and its implications for cancer onset and development are well known." (PMID 33171874, 2020). "In particular Gab2 is overexpressed in breast, gastric and lung cancers, while its expression in healthy mature cells is relatively suppressed." (PMID 32528972, 2020). "GAB2 is a scaffolding protein directly linking receptor tyrosine kinase stimulation to the cancer-relevant ERK and PI3K-AKT pathways." (PMID 32681005, 2020). "GAB2 is a key member of adaptor protein family and plays an important role in the tumorigenesis and progression of various human cancers." (PMID 28558797, 2017). "Gab2 that is selected by FRMT as the most informative protein in the READ dataset is recently introduced as an overexpressed protein in several cancer types." (PMID 28934234, 2017). "Gab2 (gene: GAB2) is an adaptor protein that is important for cancer-signaling transduction processes, including ERK signaling and PI3K-AKT signaling." (PMID 28984208, 2017). "Gab2 is a large disordered protein that regulates several cellular signalling pathways and is overexpressed in different forms of cancer." (PMID 29137268, 2017). "Our current work revealed that Gab2 exerted its role as oncogene in CRC by facilitating cancer cell migration and invasion." (PMID 26754532, 2016). "In the present review, the role of Gab2 protein in signal transduction and its emerging role in cancer are discussed." (PMID 26095858, 2015). "The present review aimed to focus on the structure and effector function of Gab2, its role in cancer and its potential for use as an effective therapeutic target." (PMID 26095858, 2015). "Gab2 contributes to an invasive and metastatic phenotype in breast carcinogenesis and is known as a potential therapeutic target in cancer therapy." (PMID 25290670, 2014). "This study identified overexpression of the signaling-coordinator GAB2 as a progression event that may mechanistically link initiating and cooperating mutations in AML and other cancers." (PMID 40773291, 2025). "A variety of cancers were discovered to have GAB2 amplification alteration." (PMID 38995439, 2024). "In addition, we utilized cBioPortal to examine the impact of GAB2 alterations on OS across multiple cancer types." (PMID 38995439, 2024). "We utilized the CPTAC database to examine the expression of phosphorylated GAB2 in pan-cancer." (PMID 38995439, 2024). "Evidence suggests that Gab2 is regulated by the PI3K pathway in cancers." (PMID 35457074, 2022). "Gab2 was found overexpressed in breast, gastric and lung cancers." (PMID 33171874, 2020). "Both in vitro and in cellula experiments confirm that the lead compound successfully interfere with the binding between the C-SH3 domain of Grb2 and a peptide mimicking the 503 to 524 sequence of Gab2 and highlight its capability to inhibit the growth of cancer cell lines." (PMID 33171874, 2020). "In particular, Gab2 is overexpressed in breast, gastric and lung cancers." (PMID 29137268, 2017). "In carcinogenesis, Gab2 engages various signaling pathways in different types of cancer." (PMID 28842424, 2017). "Additionally, we provide evidence supporting the involvement of Gab2 in the regulation of EMT in cancer." (PMID 26754532, 2016). "Our results shed new light on the role of Gab2 in the promotion of cancer metastasis." (PMID 26754532, 2016). "Gab2 has recently been proposed to be a critical molecule in the regulation of cancer metastasis, although the exact mechanism of Gab2 in metastasis remains unclear." (PMID 26754532, 2016). "Moreover, the dimer downregulates the expression of Bromodomain‐containing protein 4 (BRD4), GRB2‐associated‐binding protein 2 (GAB2), and Insulin receptor substrate 2 (IRS2) proteins, all of which play crucial roles in cancer cell sustainability and progression." (PMID 40285526, 2025).
cancer (continued). "However, we found that murine HGF is not completely inactive on human airway epithelial cells or cancer cell lines but stimulates the phosphorylation of GRB2-associated-binding protein 2 (GAB2) and signal transducer and activator of transcription 6 (STAT6)." (PMID 29771943, 2018). "To begin to assess the essentiality of GAB2 for human AML, we evaluated available CRISPR-knockout data in human cancer cell lines from the Broad DepMap database." (PMID 40773291, 2025). "A critical PPI, controlling cell growth and proliferation in breast and other cancers, occurs between growth factor receptor‐bound protein 2 (Grb2) and a polyproline II (PPII) helix embedded in Gab2." (PMID 40377959, 2025). "The phosphorylated GAB2 combines with the p85 subunit of PI3K, and then plays a role in promoting cancer." (PMID 38995439, 2024). "We used the TIMER database to analyze the relationship between GAB2 and the degree of infiltration of B cells, CD4+ T cells, CD8+ T cells, neutrophils, macrophages, and dendritic cells in pan-cancer." (PMID 38995439, 2024). "Based on the TCGA database, we used Kaplan–Meier Plotter to analyze the relationship between GAB2 expression and OS and RFS in pan-cancer." (PMID 38995439, 2024). "When Gab2 is stimulated, it interacts with SH2-domain-containing proteins, thus promoting the migration and invasiveness of cancer cells." (PMID 35457074, 2022). "BEDMR loci are further associated with local hypomethylation (66%), concentrations of the Alu SINE repeats within 3 Mb (35% of the cases), and tend to occur near a number of cancer related genes such as the protocadherins, AKT1, DUB3, GAB2." (PMID 23293768, 2012). "Indeed, published work indicates that the inhibition of BRD4, GAB2, or IRS2 restrains the progression of several types of cancer." (PMID 40285526, 2025). "We used Kaplan–Meier Plotter to analyze the relationship between GAB2 and OS and RFS in pan-cancer." (PMID 38995439, 2024). "To determine whether pY sites of GAB1 and GAB2 exhibit the same pattern of response in other cellular contexts, we also treated other EGFR-driven cancer cell lines with SHP099." (PMID 33755016, 2021).
hematologic malignancies (4 papers, 2010 to 2022). "In contrast, a requirement for Gab2 might arise in the context of the increased proliferative stress in hematological disorders." (PMID 34903841, 2022). "A better understanding of the importance of STAT5/Gab2 signals may lead to new approaches for non-ablative HSC transplantation or therapeutics for hematologic malignancies where HSC survival and self-renewal are dysregulated." (PMID 20161778, 2010).
infection (4 papers, 2010 to 2019). The state of being infected such as from the introduction of a foreign agent such as serum, vaccine, antigenic substance or organism. "Protein level of GAB2 began to decrease at 5 h and disappeared at 7 h post-infection, accompanied by the generation of an additional band at around 60 kDa using an antibody against the C-terminus of GAB2, suggesting a possible cleavage event." (PMID 28361043, 2017). "To confirm the inhibitory effects of shGAB2s to be GAB2 gene-specific, we performed a rescue experiment in which we transduce FUOV1 cells to stably overexpress GAB2 ORF or a control vector followed by infection with shGAB2s (which target the 3′-UTR of endogenous GAB2 mRNA)." (PMID 26657155, 2016). "Although Gab2 null mice still develop erythroleukemia after infection with SFFV-P, progression of the disease is much slower, with significantly less splenomegaly observed at two weeks after infection, similar to that observed in SFFV-P-infected mice deficient in the p85α subunit of PI 3-kinase." (PMID 21994618, 2010).
GAB2 also shares sentences with these, for which no sentence is quoted: acute lymphoblastic leukemia (3 papers); Bladder (2); Cerebral ischemia (2); fibrosarcoma (2); metastatic melanoma (2); amyotrophic lateral sclerosis (1); Ascites (1); autism (1); autoimmune disease (1); brain tumor (1); cardiovascular disease (1); chlamydial infections (1); Chronic colitis (1); coronary heart disease (1); Crohn disease (1); deep vein thrombosis (1); endometrial cancer (1); esophageal adenocarcinoma (1); ganglioglioma (1); glioblastoma (1); Hepatosplenomegaly (1); hypothyroidism (1); juvenile myelomonocytic leukemia (1); Kawasaki disease (1); liver fibrosis (1); mental retardation (1); multiple myeloma (1); myasthenia gravis (1); myocardial infarction (1); neurodegenerative disease (1).
A further 6 diseases each share a sentence with GAB2 in 1 paper.